MIR6124 (microRNA 6124)
Synonyms: hsa-mir-6124
Gene: MicroRNA gene on chromosome 11 (12,163,683 to 12,163,767, forward strand). Ensembl gene ENSG00000275373.
Homologues: Orthologues: chimpanzee MIR6124 (100% identical).